CLEC5A (C-type lectin domain containing 5A)
Diseases named in the same sentence as CLEC5A in open-access papers (continued):
Sharing a sentence is not in itself a finding about the gene and the disease.
infection (continued). "After anti-CLEC5A mAb treatment, approximately 50% of JEV-infected Stat1−/− mice became asymptomatic and survived for at least 21 days post infection, while the others remained weak and died gradually within 12 days." (PMID 22536153, 2012). "Even though the direct relevance of this Stat1−/− mouse model in relation to human infection with JEV needs to be further confirmed, data for in vivo protection of CLEC5A mAbs still shed light on its therapeutic potential for blocking neuroinflammation." (PMID 22536153, 2012). "It is interesting to note that virus was cleared from the spleen and CNS at day 21 post infection in surviving mice, suggesting that the host can eradicate JEV after anti-CLEC5A mAb treatment." (PMID 22536153, 2012). "No doubt that CLEC5A can trigger myeloid cell-related immune response and correlates with diverse infection and inflammatory diseases." (PMID 35979347, 2022). "Anti-CLEC5A mAb reduced viral load in the brain at day 5–7 (p = 0.009) but was ineffective in spleen, correlating with reduced NS3 expression in the brain at day 5 post infection." (PMID 22536153, 2012). "All the mice that survived JEV-induced lethality were found to have sero-conversion from day 12 post infection, suggesting that suppression of JEV-induced inflammation by anti-CLEC5A mAb did not prevent development of humoral immunity against the virus." (PMID 22536153, 2012). "Similarly, P. aeruginosa caused extensive NET formation and cellular infiltration via CLEC5A; blockade of CLEC5A reduced these effects without attenuating TLR-mediated cytotoxicity, thereby attenuating lung damage and increasing host survival after infection with P. aeruginosa." (PMID 36048544, 2022).
tumor (21 papers, 2012 to 2026). "Using an RCAS/tv-a GBM model with bone marrow transplantation from Clec5a-/- donor mice, we demonstrated that CLEC5A loss prolongs survival, delays tumor progression, and attenuates TME immunosuppression." (PMID 42228429, 2026). "The CLEC5A surface expression appeared the highest on proinflammatory M1 macrophages while intermediate on tumor-associated phenotypes (M2c or TAM)." (PMID 35252461, 2022). "Mutation analysis showed that the tumor mutational burden (TMB) was significantly increased in OC patients with high expression of CLEC5A." (PMID 34712666, 2021). "Additionally, CLEC5A is highly expressed in inflammatory M1-polarized myeloid cells but shows moderate expression in tumor-associated phenotypes (M2c or TAM)." (PMID 41415292, 2025). "It implicated that CLEC5A is related to tumor initiation and metastasis." (PMID 35979347, 2022). "In the hypoxic Pseudo.A region, ITGA5 and SDC4 showed enhanced abundance in subtype 2 TCs in comparison to CLEC5A which was enriched in tumor infiltrating MG/MØs, and LGALS3 that was overall higher in both TCs and surrounding stromal cell types." (PMID 41366031, 2025). "Similar to the gene expression analysis of BM CD11b+ cells isolated from Egfl6 mice, CD11b+ cells isolated from 2F8c-Egfl6 tumors displayed higher IL10, Cxcl2, Clec5a, and Ceacam1 gene expression compared with tumor controls." (PMID 39312740, 2024). "To identify the role of CLEC5A in the immune infiltration process, we evaluated the correlation between CLEC5A expression and immune and stromal components and tumor purity in pan-cancer." (PMID 35979347, 2022). "In general, this study contributes to a comprehensive understanding of the critical role of CLEC5A in tumorigenesis and tumor immunity and provides candidate drugs based on CLEC5A as anti-tumor therapeutic targets." (PMID 35979347, 2022). "We then compared the CLEC5A expression level across different tumor cell lines between pre- and post-ICB treatment and responders and non-responders." (PMID 35979347, 2022). "Tumor mutation burden (TMB), microsatellite instability (MSI), and neoantigens show a positive association with CLEC5A expression in several cancers." (PMID 35979347, 2022). "CLEC5A expression was significantly associated with TTN and CDK12 mutations and affected the copy number of tumor progression and immune-related genes." (PMID 34712666, 2021). "Considering the correlation of Akt pathway and tumour cell proliferation, we consequently determined the modulation of CLEC5A on total Akt and phosphorylated Akt, which presented the endogenous activity of Akt pathway." (PMID 30834619, 2019). "We determined the expression of CLEC5A in OS tumor tissues and the adjacent normal tissues by RT‐PCR and Western blotting." (PMID 31364785, 2019). "To explore the relationship between CLEC5A and OS, we determined the mRNA level and protein expression of CLEC5A in tumor tissues and the adjacent normal tissues by RT‐PCR and Western blotting, respectively." (PMID 31364785, 2019). "Based on the in vitro results, we further validated the role of CLEC5A in modulation of tumorigenesis in vivo by subcutaneous injection U251 cells containing shCLEC5A or scramble shRNA in nude mice and observed the tumour growth status." (PMID 30834619, 2019). "The in vivo results exhibited that inhibition of CLEC5A markedly inhibited tumour growth in mice, which was consistent with the in vitro studies." (PMID 30834619, 2019). "Results showed the expression of CLEC5A was markedly decreased in tumor tissues compared with the normal tissues." (PMID 31364785, 2019). "The results showed that the alteration frequency of CLEC5A varies with tumor type." (PMID 35979347, 2022). "CLEC5A is a potential prognostic biomarker of diverse cancers and a target for anti-tumor therapy." (PMID 35979347, 2022).
tumor (continued). "The strong correlation between CLEC5A and immune checkpoints suggested that CLEC5A might be an ideal tumor immunotherapeutic target and play specific roles in tumor immunotherapy response and outcome." (PMID 35979347, 2022). "In summary, we proved that CLEC5A expression is associated with immune infiltration and affects immunotherapy sensitivity patient’s prognosis in pan-cancer, suggesting that CLEC5A can serve as a biomarker for tumor immunity and prognosis of a potential promising anti-tumor therapeutic target." (PMID 35979347, 2022). "Moreover, CLEC5A mRNA expression was highly expressed in immortal tumor cell lines, such as U937, HL-60, and NB-4." (PMID 35979347, 2022). "In addition, we revealed potential therapeutic agents by analyzing the correlation between CLEC5A expression and drug sensitivity, which verified the role of CLEC5A as a potential target for tumor treatment." (PMID 35979347, 2022). "The strong correlation between CLEC5A and immune checkpoints suggested that CLEC5A might be an ideal tumor immunotherapeutic target and play certain roles in tumor immunotherapy response and outcome." (PMID 35979347, 2022). "Similarly, the protein expression of CLEC5A in tumor tissues was also markedly decreased compared with the normal tissues." (PMID 31364785, 2019). "In addition, we conducted tumour metastasis study by administration U251 cells containing shCLEC5A as well as U87 cells with lentivirus infected CLEC5A in cohort with control cells through tail vein injection and observed the lung metastasis level." (PMID 30834619, 2019). "Moreover, In vivo results suggested that inhibition of CLEC5A significantly reduced tumour size, weight, cell proliferation ability and lung metastasis via inhibition of phosphorylation Akt." (PMID 30834619, 2019). "According to the gene expression, survival analysis, mutation analysis, and immune infiltration analysis of CLEC5A in pan-cancer, we confirmed that CLEC5A might play an essential role in tumorigenesis and tumor immunity, suggesting its enormous potential as a tumor therapeutic target." (PMID 35979347, 2022). "Moreover, our study showed CLEC5A plays a role in tumor inhibition in the metastasis of OS." (PMID 31364785, 2019). "Moreover, in nude mice, CLEC5A knockdown significantly decreased tumour growth and metastasis." (PMID 30834619, 2019). "Immunochemistry staining of Ki‐67, a proliferation marker commonly used in pathological assessment, showed that tumour generated by shCLEC5A cells had lower level of Ki‐67, which further support the hypothesis that knockdown of CLEC5A inhibited tumour cell growth." (PMID 30834619, 2019). "To select the genes that are most closely related to tumor immunity from these key prognostic genes, we further combined with the DEGs based on ESTIMATE analysis to screen CLEC5A as the key prognostic gene." (PMID 34712666, 2021). "Moreover, knockdown of CLEC5A downregulated protein level of MMP‐2, MMP‐9, PCNA and Akt phosphorylation in tumour tissues." (PMID 30834619, 2019). "Because CLEC5A is also responsible for ConA-induced shock syndrome and synovial inflammation in collagen-induced arthritis, thus bloackade of CLEC5A/TLR2 may reduce bacteria-induced systemic permeability change, inhibit tumor metastasis, and attenuate tissue damages during aseptic inflammation." (PMID 31867016, 2019).
cancer (8 papers, 2019 to 2025). A tumor composed of atypical neoplastic, often pleomorphic cells that invade other tissues. "Studies have shown that CLEC5A is positively related to immune infiltration, including macrophages, cancer-associated fibroblasts, and regulatory T cells." (PMID 38979413, 2024). "In this study, CLEC5A gene alteration occurs in most cancer types, predominately amplification, followed by mutation." (PMID 35979347, 2022). "The results showed that CLEC5A expression was positively correlated with the immune infiltration levels of macrophages, cancer associated fibroblast, and Tregs, and negatively correlated with MDSC abundance." (PMID 35979347, 2022). "Altogether, this may suggest that the elevated CLEC5A protein expression on myeloid cells is rather associated with a proinflammatory condition in contrast to normal tissue or cancer." (PMID 35252461, 2022). "Besides, we obtained a mutation pattern of CLEC5A in various cancers using the cBioportal tools, and the results coincided with the waterfall plots obtained by GSCALite." (PMID 35979347, 2022). "Immune checkpoint genes are significantly associated with CLEC5A expression in diverse cancers." (PMID 35979347, 2022). "Moreover, CLEC5A is positively related to immune infiltration, including macrophages, cancer-associated fibroblasts (CAFs), and regulatory T cells (Tregs)." (PMID 35979347, 2022). "Further, it has been demonstrated that, in certain types of cancers, Clec5a promotes tumorigenesis through the activation of the PI3K/AKT pathway." (PMID 41300301, 2025). "In contrast, up-regulation of other members from this superfamily such as CLEC18B, CLEC5A, CLEC4A, and CLEC4L were reported to be associated with development, proliferation, migration, and invasion in cancer cells." (PMID 38167030, 2024). "CLEC5A is differentially expressed in a few cancer types, of which overexpression accompanies low overall survival of patients." (PMID 35979347, 2022). "Previous studies indicated that CLEC5A is overexpressed in some cancers and involves tumorigenesis and progression." (PMID 35979347, 2022). "CLEC5A expression in most cancers was positively correlated with the expression of ICPs, especially in LGG, OV, PAAD, and THCA and more than 30 immune checkpoints were positively correlated with CLEC5A expression." (PMID 35979347, 2022). "We implemented the functional enrichment analysis to identify the biological roles of CLEC5A in pan-cancer." (PMID 35979347, 2022). "The pie chart showed that the heterozygous CNVs of all 6 genes (CD68, MRC1, CD8A, CD8B, CD163, and CLEC5A) was more frequent in various cancers." (PMID 35979347, 2022). "KEGG enrichment analysis revealed that CLEC5A-related partners in pan-cancer were involved in B cell receptor signaling, T cell receptor signaling, and JAK-STAT signaling." (PMID 35979347, 2022). "GSCALite was utilized to identify the SNV frequency of all 6 genes (CD68, MRC1, CD8A, CD8B, CD163, and CLEC5A) in various cancers." (PMID 35979347, 2022). "We investigated the correlation between CLEC5A expression and four essential DNMTs expressions in pan-cancer." (PMID 35979347, 2022). "We next explored the correlation between CLEC5A expression and the prognosis of patients with pan-cancer." (PMID 35979347, 2022). "The CLEC5A expression in M2 macrophages in BRCA and HNSCC was higher than that in other cell types, while the CLEC5A expression in M1 macrophages and cancer cells in OV was higher than that in different types." (PMID 35979347, 2022). "In line with the findings on in vitro differentiated TAMs, the ex vivo-derived cancer-related macrophages showed only very low CLEC5A expression." (PMID 35252461, 2022). "First, we comprehensively analyzed the CLEC5A expression in tumors and paired normal tissues in different cancers with TCGA and GTEx gene expression data." (PMID 35979347, 2022).
cancer (continued). "CLEC5A mediated activation of the EMT signaling pathway in 35% of cancers, while CLEC5A mediated inhibition of DNA damage response and hormone AR pathway in 18% and 25% of cancers, respectively." (PMID 35979347, 2022). "We found that in specific cancer types, the CLEC5A expression also significantly correlated with TMB, MSI, and neoantigens." (PMID 35979347, 2022). "Furthermore, CLEC5A expression correlates with several critical aspects of cancer biology, such as epithelial-mesenchymal transition (EMT) and apoptosis processes." (PMID 38979413, 2024). "Furthermore, CLEC5A in cancer correlates with signal transduction, the immune system, EMT, and apoptosis process." (PMID 35979347, 2022). "The results implicated that CLEC5A expression was positively correlated with immune infiltration levels of macrophages, CAF, and Tregs, whereas it is negatively correlated with MDSC in most cancer types." (PMID 35979347, 2022). "In addition, CLEC5A mRNA expression was up-regulated in 22 other cancer types and down-regulated in only 4 tumors (ACC, KICH, LUSC, and PRAD)." (PMID 35979347, 2022). "We found that gene mutations and methylation levels of CLEC5A can lead to abnormally high CLEC5A expression, which is significantly associated with increased immune infiltration of macrophages, CAF, and Treg and poor prognosis of various cancers." (PMID 35979347, 2022). "Furthermore, we explored the relationship between CLEC5A expression and specific immune cells infiltration in human cancer." (PMID 35979347, 2022). "More recently, CLEC5A has emerged as a pivotal contributor to cancer development and progression." (PMID 35979347, 2022). "A pan-cancer analysis has indicated that CLEC5A could predict cancer immunity and prognosis." (PMID 39553729, 2024). "Moreover, GSVA of GO terms related to CLEC5A expression was performed in pan-cancer." (PMID 35979347, 2022). "Therefore, CLEC5A differential expression in most cancer types indicates that CLEC5A may play a key role in carcinogenesis." (PMID 35979347, 2022). "Whether CLEC5A can be a target for cancer treatment still needs more experimental exploration." (PMID 35979347, 2022). "In addition, CLEC5A expression correlates with mismatch repair (MMR) in several cancers." (PMID 35979347, 2022). "We identified heightened expression of TLR2 as well as CLEC5A and CLEC4E in cancer samples in general and in the subgroup." (PMID 38979413, 2024). "Next, we evaluated the correlation between the DNA methylation and mRNA expression of CLEC5A and immune-related gene (MRC1, CD163, CD8A, CD8B, CD68) in pan-cancer." (PMID 35979347, 2022). "Nevertheless, a broader study including more patients and different cancer types would be necessary to elaborate on a potential role of CLEC5A (or lack of thereof) in cancer." (PMID 35252461, 2022). "Thus, the DNA methylation differences of CLEC5A and immune-related gene (MRC1, CD163, CD8A, CD8B, CD68) between tumors and normal tissues in various cancers were evaluated with the GSCALite platform." (PMID 35979347, 2022).
bacterial infections (5 papers, 2017 to 2025). "A recent study finds CLEC5A, which has long been associated with dengue virus-induced lethal disease, to be an important factor associated with modulating innate immune response against bacterial infection in mice." (PMID 33692779, 2021). "In this study, we investigated the role of CLEC5A in the innate immune response to bacterial infection using L. monocytogenes (a Gram-positive, intracellular bacterium) as a model system." (PMID 28824166, 2017). "C-Type lectin receptor 5A (CLEC5A) is a spleen tyrosine kinase- (Syk-) coupled pattern recognition receptor expressed on myeloid cells and involved in the innate immune response to viral and bacterial infections." (PMID 35252461, 2022). "Since CCR2+ inflammatory monocytes mediate host defense against bacterial infection, we investigated whether this cell population was functionally impaired in Clec5a−/− and Clec5a−/−Tlr2−/− mice." (PMID 28824166, 2017). "Since IL-1β is critical for host defense against bacterial infections in general, we investigated whether CLEC5A is required for IL-1β production in response to other bacteria." (PMID 28824166, 2017).
inflammation (4 papers, 2014 to 2022). Aberrant reaction of the microcirculation characterized by movement of fluid and leukocytes from the blood into extravascular tissues. "Moreover, blockade of CLEC5A by an antagonistic anti-CLEC5A mAb attenuates pulmonary inflammation and increases host survival during P. aeruginosa infection." (PMID 36048544, 2022). "Interestingly, during joint inflammation, overexpression of CLEC5A/MDL-1 recruits inflammatory cells and induces the production of IL-1, IL-6, IL-17A, and TNF, contributing to cartilage damage and bone erosion." (PMID 26086874, 2015).
immune disorder (2 papers, 2015 to 2022). "The results showed that CLEC5A is highly associated with nervous system diseases, immune system diseases, infectious diseases, and musculoskeletal or musculoskeletal or connective tissue diseases." (PMID 35979347, 2022). "In the present study, JQ1 also significantly inhibited Mmp13, Clec5a, and Gpr84 expression, and these inhibitory effects of JQ1 may play a potential role in immune disorder treatment, possibly through inhibition of macrophages and the ensuing inflammatory responses." (PMID 26582142, 2015).
CLEC5A also shares sentences with these, for which no sentence is quoted: Arthritis (3 papers); atherosclerosis (3); Flavivirus Infections (2); Japanese encephalitis (2); malaria (2); rectal cancer (2); acute lung injury (1); acute respiratory distress syndrome (1); adenovirus infection (1); Alzheimer disease (1); astrocytoma (1); Autoimmunity (1); brain tumour (1); coagulopathy (1); colorectal cancer (1); connective tissue diseases (1); coronary artery disease (1); endometrial cancer (1); endothelial dysfunction (1); epididymitis (1); infectious disease (1); multiple sclerosis (1); nervous system diseases (1); osteoarthritis (1); otitis media (1); papillary thyroid carcinoma (1); spinal cord injury (1); Still's Disease (1); systemic inflammatory response syndrome (1); testicular germ cell tumor (1).
A further 1 disease shares a sentence with CLEC5A in 1 paper.